CFAP92 (cilia and flagella associated protein 92 (putative))
Synonyms: KIAA1257; FLJ43738; FAP92
Tractability: No criterion of Open Targets' tractability assessment is met for any kind of drug.
Gene: Protein-coding gene on chromosome 3 (128,909,866 to 129,002,690, reverse strand). Ensembl gene ENSG00000114656.
Genetic constraint (gnomAD): Loss-of-function variants: 82 observed, 102.74 expected, observed/expected ratio (o/e) 0.8, 90% interval 0.67 to 0.96. The upper end of that interval is the gene's LOEUF score, 0.96, which puts it in group 4 of 6, group 1 being the genes least tolerant of losing a copy. Missense variants: 1,180 observed, 1,279.3 expected, observed/expected ratio (o/e) 0.92, 90% interval 0.88 to 0.97. Synonymous variants: 469 observed, 510.12 expected, observed/expected ratio (o/e) 0.92, 90% interval 0.85 to 0.99.
Homologues: Orthologues: macaque CFAP92 (95% identical), dog CFAP92 (68% identical), pig CFAP92 (64% identical), rabbit CFAP92 (63% identical), mouse Cfap92 (63% identical), rat Cfap92 (62% identical), tropical clawed frog cfap92 (31% identical), zebrafish cfap92 (26% identical).